CCL20 (C-C motif chemokine ligand 20)
Diseases named in the same sentence as CCL20 in open-access papers (continued):
Sharing a sentence is not in itself a finding about the gene and the disease.
glioblastoma (12 papers, 2018 to 2026). The most malignant astrocytic tumor (WHO grade IV). "For instance, its role in promoting glioblastoma growth is known; it acts by recruiting tumor-associated macrophages through increased expression of CCL20." (PMID 38927057, 2024). "A prior study has identified CCL20 expression by immunohistochemistry within human glioblastoma tissues, and this has correlated with increased T-cell infiltration." (PMID 35464424, 2022). "Notably however, CCL20 was limited to the cytoplasm of tumour cells, with little secreted in the glioblastoma microenvironment." (PMID 35464424, 2022). "We next validated and quantified the CCL20 levels in glioblastomas using Elisa." (PMID 33483477, 2021). "When considering the CCR6–CCL20 axis for therapeutic targeting in glioblastoma, CD8+CCR6+ T cells also migrate towards CCL20 and blockade of CCL20 or CCR6 has also been demonstrated to reduce neuroinflammation in murine models of subarachnoid hemorrhage." (PMID 34771532, 2021). "B. The levels of CCL20 and IL-17A in sera from CRC patients, lung adenocarcinoma [LUAD] patients, glioblastoma [GBM] patients and controls (Healthy donors [HD]) were tested by Elisa (*P < 0.05; **P < 0.01; ***P < 0.001)." (PMID 31387598, 2019). "Despite high proportions of T cells and non-lymphocyte populations identified as positive for CCR6 and CCL20 via scRNA-seq respectively, CCR6+ T cells were not enriched in glioblastoma and we were unable to detect CCL20 in supernatants via ELISA." (PMID 35464424, 2022). "There, genes with a higher expression in glioblastoma compared to astrocytoma were VEGFA, 4EBP1, CCL2, PLAU (uPA), CXCL8 (IL8), CXCL10 (IP10), CASP8, HGF, LIF, CD40, CDCp1, TNFRSF11B (OPG), CD274 (PD-L1), IL6, CXCL1, CCL20 (MIP3α), CCL8 (MCP2), CD244, MMP1, TNFRSF9, CXCL6, MMP10, FGF5)." (PMID 35301393, 2022). "This may explain why we did not detect CCL20 by ELISA in supernatants from dissociated glioblastoma specimens or GNS cells." (PMID 35464424, 2022). "While most of the analyzed chemokines (listed in Section 2) were not released by ferroptotic glioblastoma cells, we detected variations for CXCL1, CCL18, CCL20, and CCL22; however, these were not significant when comparing RSL3 to RSL3/liproxstatin-1." (PMID 41300529, 2025).
ulcerative colitis (12 papers, 2009 to 2025). An inflammatory bowel disease involving the mucosal surface of the large intestine and rectum. "Like in HCs, we found that VD deficiency was associated with higher serum CCL20 levels in patients with ulcerative colitis." (PMID 40542081, 2025). "At the 2q36.3 locus associated with Ulcerative colitis, rs1811711 was fine mapped with 94% probability and was a caQTL in T cells and monocytes and was reported as eQTL for the nearby gene CCL20 in whole blood." (PMID 37289818, 2023). "Compared to healthy controls, Crohn’s disease patients and ulcerative colitis patients exhibited significantly higher circulating CCL20 levels." (PMID 40542081, 2025). "The potent upregulation of epithelial CCL20, observed in active ulcerative colitis and Crohn’s disease, is primarily induced by TLR3 ligation with dsRNA14." (PMID 40542081, 2025). "The transcriptome analysis shows that expression of CCL20 is potently induced in active ulcerative colitis and active Crohn’s disease, while expression levels in inactive disease are indistinguishable from healthy controls." (PMID 26536229, 2015). "CCL20 and CCR6 mRNA abundances were increased during active inflammation (CCL20 5.4-fold in ulcerative colitis and 4.2-fold in Crohn’s disease; CCR6 1.8 and 2.0, respectively)." (PMID 26536229, 2015). "Genes up-regulated by C. jejuni that have been associated with active ulcerative colitis/IBD include chemokines, such as IL8 and CCL20 (macrophage inflammatory protein 3α) cytokines, including TNFα, eicosanoids and elafin." (PMID 19193236, 2009). "However, in HCs and ulcerative colitis patients with sufficient 25-hydroxyvitamin D serum status, a higher calcitriol/25-hydroxyvitamin D activation ratio correlated with lower systemic CCL20 levels." (PMID 40542081, 2025). "By attracting additional immune cells, as well as inducing proinflammatory IL-1β release from immune cells, CCL20 may protract the inflammatory response in ulcerative colitis." (PMID 30347808, 2018). "The present study aimed to clarify whether the expression of CCL20 and its receptor, CCR6, was correlated with the development of ulcerative colitis (UC)-associated neoplasia." (PMID 24179507, 2013). "Noteworthy, the expression of CCL20 has been found significantly up-regulated in PBMCs of patients with ulcerative colitis and Chron's Disease, being the role of CCL20 to link innate and adaptive immunity by attracting immature dendritic cells, effector memory T cells and B cells." (PMID 23527089, 2013). "In a cross-sectional study, serum concentrations of CCL20, 25-hydroxyvitamin D, and calcitriol were measured in 170 NOD2-genotyped Crohn’s disease patients, 80 ulcerative colitis patients, and 60 healthy controls." (PMID 40542081, 2025). "The aim of this study is to clarify the differences of CCL20 and CCR6 expression, chemokine correlated to intestinal homeostasis, between pediatric and adult ulcerative colitis (UC) patients." (PMID 25691899, 2015). "In conclusion, this study shows that epithelial CCL20 is potently upregulated in active ulcerative colitis and Crohn’s disease, but not in inactive disease." (PMID 26536229, 2015). "Existing knowledge is somewhat conflicting, both with regard to whether only ulcerative colitis or Crohn’s disease, or both forms of IBD, exhibit CCL20 involvement, and whether this is found only in active disease or not." (PMID 26536229, 2015). "This is somewhat at odds with previous results, which have shown either CCL20 overexpression in only Crohn’s disease and not ulcerative colitis, or also in inactive disease." (PMID 26536229, 2015).
atherosclerosis (11 papers, 2007 to 2024). A disease characterized by the build-up of fatty material and calcium deposition in the arterial wall resulting in partial or complete occlusion of the arterial lumen. "The migration relies on the CCR6-CCL20 pathway, meanwhile CCL20 is found upregulated in hypertension damaged vessel walls and the plaque of atherosclerosis." (PMID 35629392, 2022). "CCL20, a chemokine that attracts immature dendritic cells, effector/memory T cells, and naive B cells, has been observed at elevated levels in patients with atherosclerosis." (PMID 39465855, 2024). "CCR6 and its ligand CCL20 have emerged as important regulators of atherosclerosis." (PMID 33679793, 2021). "Also, circulating levels of CCL20 is significantly increased in hypercholesterolemic patients and LDL stimulated vascular smooth muscle cells express CCL20 and promote human lymphocyte migration, implicating a role for the CCR6-CCL20 axis in atherosclerosis development." (PMID 33679793, 2021). "We noted a significant upregulation between MYD88 and CCL20 (G60); IFNβ (G90); NF-kB, IL18 (G120); NF-kB, CCR2, IL1b, IL18 (GF120); and CCR2 (GR120) in the thoracic aorta during the inflammatory process of atherosclerosis." (PMID 37298199, 2023). "In human atherosclerosis, the expression of CCR6 and CCL20 in atherosclerotic lesions in the coronary and carotid arteries has been reported." (PMID 33679793, 2021). "It signals via the Ccr6 receptor and the importance of the CCL20/Ccr6 axis for development of atherosclerosis was demonstrated in ApoE−/− mice lacking Ccr6, which had reduced size of the atherosclerotic lesions." (PMID 38350853, 2024). "This mouse model may constitute an important tool for research on liver inflammation and on any diseases where CCL20 may constitute an important element of the pathophysiology, such as NASH autoimmune hepatitis sterile inflammation and atherosclerosis or ischemia reperfusion injury." (PMID 24265691, 2013).
lymphoma (11 papers, 2009 to 2024). A malignant (clonal) proliferation of B- lymphocytes or T- lymphocytes which involves the lymph nodes, bone marrow and/or extranodal sites. "On the other hand, overexpression of CCR6 in lymphoma cells might possibly drive tumor growth through CCL20-mediated recruitment of tumor-associated macrophages." (PMID 33288848, 2020). "In this clinical trial, we intend to use recombinant plasmid DNA encoding a fusion protein consisting of autologous lymphoma scFv and the human CCL20 (macrophage inflammatory protein-3 alpha - MIP-3α) chemokine." (PMID 29439670, 2018). "RNA-seq analysis also revealed that several different T-cell chemokines (including CCL5, CCL20, and CCL22) are over-expressed in the Δ3C virus-infected, versus WT virus-infected, lymphomas, a finding confirmed by qPCR analysis of tumor cell-derived cDNA." (PMID 30125329, 2018). "In EBV-positive HL, the lymphoma microenvironment is T-reg cell rich and the transformed cells secrete immunosuppressive cytokines and chemokines like IL10, CCL5, CCL20, and CXCL10." (PMID 22979947, 2012).
liver cancer (10 papers, 2021 to 2024). An epithelial or non-epithelial malignant neoplasm that arises from the liver. "In hypoxic microenvironment, the TREM-1-expressing M2-like TAMs recruit CCR6-containing Tregs near liver cancer cells by secreting CCL20, which is the principal cause of resistance to anti-PD-L1 immunotherapy in liver cancer." (PMID 35672862, 2022). "In line with our observations, the CCL20/CCR6 axis has been directly linked to promote carcinogenesis in several cancer entities including primary liver cancers by re-shaping the immunologic TME and subsequently migration as well as proliferation of cancer cells." (PMID 36982370, 2023). "Recently, we also found that MyD88 in HSCs/myofibroblasts promoted the progress of DEN/CCl4-induced fibrosis-related HCC via CCL20 secretion and promoted the aerobic glycolysis of liver cancer cells." (PMID 38291436, 2024). "IL-8 and CCL20 were induced by LTβR stimulation in two different liver cancer cell lines (HLE and JHH4) and in one HNSCC line (HSC3)." (PMID 39215104, 2024). "Gene expression analysis in liver cancer cell lines (HePG2) revealed that M levan decreased the expression of CCL20), 2GRB2, and CCR6) genes and was superior to Doxo." (PMID 38326332, 2024). "qRT-PCR assays were implemented and the results showed that the mRNA expression levels of CCL20 were significantly higher in liver cancer cells, like SMMC7721, Huh7, HepG2, and HCCLM3, than in normal cells, such as WLR68, and LO2." (PMID 36969014, 2023). "Where, its mode of action was explained by liver cancer-related genes such as CCL20, GRB2, and CCR6 as well as immune-related genes IL4R and IL10, and a possible correlation between the levan in lowering the anti-migratory activity and its cytotoxicity effect in HepG2." (PMID 38326332, 2024). "IL-8 and CCL20 functionally contribute to progression, invasion and metastasis of liver cancer." (PMID 39215104, 2024). "Myeloid malignancies with elevated IL1RAP and CCR6+ cancers that respond to CCL20 such as liver cancer might be first candidates." (PMID 36107259, 2022).
multiple sclerosis (10 papers, 2014 to 2024). A progressive autoimmune disorder affecting the central nervous system resulting in demyelination. "Still, it is also a CNS-homing chemokine receptor through the constitutive expression of CCL20 of the choroid plexus and has been identified as a target of interest in multiple sclerosis." (PMID 38444848, 2024). "Over the follow-up, people with multiple sclerosis had significant increase in CCL20 (9.7 pg/mL versus 15.1 pg/mL, P = 0.001) and NfL levels (10.5 pg/mL versus 11.5 pg/mL, P = 0.003)." (PMID 37361716, 2023). "In particular, myelin-specific T cell infiltration in the brain was reported to positively correlate with the expression of CCL20 in the choroid plexus of humans with multiple sclerosis or mice with experimental autoimmune encephalitis." (PMID 27336468, 2016). "Using a mouse model of chronic neuroinflammation, we report that raloxifene, a selective estrogen receptor modulator, alleviated experimental autoimmune encephalomyelitis–an animal model of multiple sclerosis–and decreased astrocytic production of CCL20." (PMID 24722370, 2014). "Epstein–Barr virus (EBV) infection and various chemokines, including CCL20, CXCL8 and CXCL10 are considered to participate in the pathogenesis of multiple sclerosis (MS), and several studies point to a direct regulatory effect of EBV on the expression of these chemokines." (PMID 39125633, 2024). "CCL20 is an inflammatory chemokine, which is upregulated during inflammation to recruit primarily CCR6-expressing leukocytes, with a well-established role in diseases such as multiple sclerosis or its animal model experimental autoimmune encephalomyelitis." (PMID 37554323, 2023).
Allergy (9 papers, 2015 to 2025). An allergy is an immune response or reaction to substances that are usually not harmful. "MIP-3α (CCL20) is known to be involved in pathogenesis of allergies of the upper respiratory tract and in steady state migration of dendritic cells in the skin." (PMID 37147507, 2023). "The expression of Ccl8, known to attract actors of allergy and inflammation, was elevated in both Spink5-/- and Spink5-/-Klk5-/- skin, whereas Ccl20, a chemoattractant for CCR6+ cells including dendritic cells and Th17 cells, showed a significant increase only in Spink5-/- skin." (PMID 26390218, 2015). "Some studies have suggested that CCL20/CCR6 interactions are important in the development of Th2 responses and allergy." (PMID 27014260, 2016).
atopic dermatitis (9 papers, 2010 to 2024). "CCL20, a chemokine important for the recruitment of Th17 cells, is suppressed in the lesions of atopic dermatitis." (PMID 38558806, 2024). "We also investigated the regulatory effects of dhAvD on CCL20 and IL-23, keratinocyte-derived factors that enhance Th2 cytokines that are highly expressed in atopic dermatitis, and their downstream molecules, MMP-9 and MMP-12." (PMID 39329899, 2024). "Both these receptors and their ligands, CXCL16 and CCL20 are reported to be overexpressed in atopic dermatitis and lesional psoriatic skin, and contribute to the skin inflammation." (PMID 34162906, 2021). "Dupilumab inhibits the IL-4/IL-13 signaling pathway to reduce itching and itching in atopic dermatitis, which may reduce the release of CCL20 from keratinocytes and also reduce Th17 cell infiltration." (PMID 35069008, 2022). "However, acknowledging the ongoing importance of LC in atopic dermatitis, additional research is needed to elucidate how significant genetic factors (Trp73, Orm-1, Chi3l3, Ccl20, AnXa1, Alox5, Ccr1, and Fcεr1a, etc.)identified in our study may interact with LC function and the disease process." (PMID 38834629, 2024). "We also revealed that activated CD8+ helper T-cell subsets induced CCL20 in keratinocytes, which was strongly enriched in psoriatic, but not atopic dermatitis lesions." (PMID 33311473, 2020). "Indeed, the macrophage inflammatory protein MIP3-α/CCL20 and the monokine induced by interferon-gamma MIG/CXCL9 were found elevated in infants with severe malaria and in patients with atopic dermatitis." (PMID 25698903, 2015).
Autoimmunity (9 papers, 2015 to 2025). The occurrence of an immune reaction against the organism's own cells or tissues. "Immunomodulation and autoimmunity: RE was associated with the downregulation of proinflammatory chemokines CXCL9 and CCL20, both linked to HT risk in our previous study." (PMID 41301428, 2025). "During inflammation, increased CCL20 expression drives the recruitment of CCR6+ immune cells to regulate the immune response, inflammatory response, autoimmunity, and alloimmunity." (PMID 36118358, 2022).
liver disease (9 papers, 2012 to 2025). "It has been postulated that certain chemokines and cytokines, especially CCL20, attract T helper 17 (Th17) lymphocytes to damaged bile ducts in various liver diseases." (PMID 37820623, 2023). "This study, together with previous data investigating the role of CCL20 in liver disease, identifies the CCL20/CCR6 pathway as an important player in liver disease." (PMID 26691857, 2015). "In light of the pivotal role of immune parameters (e.g., CXCL13, IL21, IL6, and CCL20) in the distinct microbial composition at early liver disease stages and in general with cognitive impairment, we determined which specific bacterial taxa are related to these patterns." (PMID 41035890, 2025). "Finally, increased CCR6 hepatic expression in patients with alcoholic hepatitis was found to correlate with liver expression of CCL20 and severity of liver disease." (PMID 26691857, 2015). "Th17 cells showed CCL20-dependent migration to cholangiocytes suggesting this pathway could be important in the positioning of Th17 cells in portal tracts in liver diseases." (PMID 22796894, 2012). "Selected C-X-C chemokine members of the IL-8 chemokine family and C-C chemokine CCL20 were highly associated with AH compared with HC but not in patients with liver diseases of other etiologies (nonalcoholic fatty liver disease [NAFLD] and hepatitis C virus [HCV])." (PMID 33945507, 2021). "Defining the role of chemokines and chemokine-receptors such as CCL20 and CCR6 in liver injury is of paramount importance to better understand liver disease and to develop new targeted therapeutic strategies." (PMID 26691857, 2015). "The CXCR3 ligands CXCL9–11 are known to be expressed by hepatocytes, cholangiocytes, and stellate cells in liver disease but less is known about the CCR6 ligand CCL20." (PMID 22796894, 2012). "In addition, the pathogenic role of other chemokines such as CCL2 (MCP-1), CCL17, CCL11, CCL20 and CXCL1 in liver diseases remains unclear and requires further investigation." (PMID 32641985, 2020). "A combination model composed of CCL20 and LCN2 may serve as a more efficient tool for distinguishing HCC from nonmalignant liver diseases." (PMID 35308139, 2022).
periodontitis (9 papers, 2019 to 2025). An acute or chronic inflammatory process that affects the tissues that surround and support the teeth. "In the IL-17 Signaling pathway, identified as the most suppressed CP, FOS, JUN, Matrix Metallopeptidase 13 (MMP-13), and C-C Motif Chemokine Ligand 20 (CCL20) were downregulated in periodontitis tissues (Log2FC<-1.5)." (PMID 41124422, 2025). "In patients with periodontitis, an upregulation of CCL20, a chemokine involved in cell migration, has been observed in periodontal tissues." (PMID 39131163, 2024). "Focusing on how this impacted keratinocytes, we found chemokine signatures such as CXCL1/3/8/17 and CCL20 that had been found in previous analyses, in both periodontitis and health." (PMID 38876998, 2024). "While the detrimental effects of MMPs in periodontitis have been well-documented, the role of CCL20 is controversial due to its dual biological activity as a chemokine and an antimicrobial peptide." (PMID 36776856, 2023). "Similarly, keratinocytes in periodontitis patients show increased expression of CXCL1, CXCL3, CXCL8, CXCL13, and CCL20, suggesting that chemokine expression in gingival fibroblasts and epithelial cells drives chronic periodontitis." (PMID 40565042, 2025). "P. gingivalis-Th17 cell migration aggravates periodontitis progression, indicating that inhibiting the CCL20/CCR6 axis could prevent periodontitis from developing." (PMID 39131163, 2024). "For example, Prevotella predominates in periodontitis and could exacerbate inflammatory disease by stimulating the production of inflammatory mediators such as CCL20, IL-8 and IL-6." (PMID 37808891, 2023). "Furthermore, in periodontitis tissue samples, CCL20 levels were shown to be elevated." (PMID 35408801, 2022). "It remains to be verified if CCL20 exerts antimicrobial activity against P. gingivalis or other oral pathogens, and whether this mechanism is operational in the inflamed gingival tissue during periodontitis." (PMID 31114581, 2019).